ENO1 (enolase 1)
Diseases named in the same sentence as ENO1 in open-access papers (continued):
Sharing a sentence is not in itself a finding about the gene and the disease.
glioma (54 papers, 2012 to 2025). A benign or malignant brain and spinal cord tumor that arises from glial cells (astrocytes, oligodendrocytes, ependymal cells). "Acting as a small molecule enolase inhibitor, POMHEX has the ability to selectively eliminate ENO1-deficient glioma cells at low nanomolar concentrations." (PMID 40507914, 2025). "They concluded that an overexpression of ENO1 was associated with glioma progression, while reducing ENO1 expression led to a suppression of cell growth, migration and invasion progression by inactivating the PI3K/Akt pathway in glioma cells." (PMID 39061201, 2024). "These inhibitors selectively killed ENO1-deleted glioma cells and eliminated intracranial orthotopic ENO1-deficient tumors in mice." (PMID 39088549, 2024). "ENO1 encodes α-enolase functioning in glycolytic processes; its knockdown reversed the malignant growth, and migration of glioma cells to normal levels." (PMID 36494582, 2023). "In fact, α-enolase, the protein product of ENO1, is a multifunctional protein that has been associated with metastasis in several types of cancer, including glioma." (PMID 38139462, 2023). "Other studies have shown that POMHEX, a small enolase inhibitor, selectively kills ENO1-deficient glioma cells at low nanomolar concentrations, suggesting that ENO1 acts as a promising target for inhibiting tumor progression." (PMID 36620599, 2022). "We previously demonstrated that glioma cells with ENO1 passenger deletions are selectively susceptible to inhibition of ENO1’s redundant paralog ENO2 through the collateral lethality paradigm." (PMID 34172075, 2021). "Ultimately, a key glycolytic enzyme, ENO1, was identified as target gene, in view of its upregulation is associated with glioma progression and prognosis." (PMID 34772911, 2021). "We also described the relevance of ENO1 in SNHG18-mediated glioma migration and investigated the underlying mechanisms." (PMID 31798634, 2019). "ENO1 expression is detected in most tissues and its overexpression is associated with multiple tumors, including glioma, neuroblastoma, and other types of cancers." (PMID 29497031, 2018). "To investigate the prognostic value of ENO1 expression in glioma, we assessed the association between levels of tumor ENO1 expression and patients’ survival using Kaplan-Meier analysis with the log-rank test." (PMID 24650096, 2014). "To explore its associated molecular mechanisms in glioma cells, we examined the effect of targeted silencing of ENO1 gene on cell proliferation, migration and invasion using shRNA in vitro and vivo." (PMID 24650096, 2014). "Furthermore, it was shown that broad inhibition of enolase had minimal toxicity in ENO1-intact glioma cells and normal human astrocytes while being lethal to the ENO-1 deficient cells, an appropriate setting for employing a ‘synthetic lethal’ strategy." (PMID 31745118, 2019). "ENO1 has been linked to migration and invasion of glioma cells." (PMID 26035385, 2015). "ENO1 glycolytic activity is strongly associated with increased ATP citrate lyase expression in gliomas, thus ENO1 may act as a metabolic tumor promoter conferring a selective growth advantage onto ENO1-overexpressing tumor cells." (PMID 24650096, 2014). "Overexpression of ENO1 is associated with glioma progression." (PMID 24650096, 2014). "In addition, increased ENO1 was associated disease progression in glioma samples." (PMID 24650096, 2014). "Analysis of the Cancer Cell Line Encyclopedia (CCLE) database revealed significant upregulation of ENO1 expression in most glioma cell lines." (PMID 41353343, 2025). "In the literature, POMHEX is described as a small molecule Enolase inhibitor that is aimed at targeting glycolysis in cancer and has been employed in ENO-1 deleted glioma cells." (PMID 41465295, 2025). "ENO1 expression positively correlated with WHO glioma grade (P < 0.05) and varied significantly among histological subtypes, with particularly high expression in glioblastoma." (PMID 41353343, 2025).
glioma (continued). "Analysis of 413 primary and recurrent glioma cases from the CGGA database showed significantly higher ENO1 mRNA levels in recurrent cases (P < 0.05)." (PMID 41353343, 2025). "To validate these findings, we performed Western blot analysis on six glioma cell lines, which confirmed varying degrees of ENO1 upregulation." (PMID 41353343, 2025). "Song and colleagues (2015) analyzed the involvement of ENO1 in tumor progression and the prognosis of human glioma." (PMID 39061201, 2024). "One of the lead compounds, HEX, had an EC50 value of 1.3 μM against ENO1-/- glioma cells but was very well-tolerated by ENO1-rescued glioma and other control cells, with CC50 values >300 μM." (PMID 39088549, 2024). "Intriguingly, with its direct role in glycolysis, enolase-1 promotes cell proliferation by regulating the PI3K/AKT signaling pathway and is associated with glioma progression." (PMID 39267734, 2024). "For example, glioma cells carrying a large deletion including the ENO1 gene cannot survive when the paralogue ENO2 was inhibited." (PMID 37984988, 2024). "Then, they used gliomas with deletion of ENO1, but sensible to enolase inhibitors because of the expression of ENO2." (PMID 38139462, 2023). "Taking advantage of deletions of ENO1 which can occur in some types of tumors including glioma, pan-ENO inhibitors were evaluated as SF2312 and also combined with pivaloyloxymethyl (POM) to form POMSF and POMHEX, a less toxic version of the inhibitor." (PMID 38139462, 2023). "The treatment with POHMEX was used then as a successful and effective antineoplastic approach in ENO1-homozygously deleted glioma." (PMID 38139462, 2023). "Localized at the nucleus, ENO1 can inhibit transcription of the original cancer gene c-myc, and interfering with ENO1 expression can inhibit the growth, migration and invasion of glioma cells." (PMID 36295613, 2022). "Recent studies on glioma also confirmed that silenced ENO1 expression can significantly inhibit glucose intake, lactic acid production, extracellular acidification rate, and the angiogenesis ability of glioma microvascular endothelial cells." (PMID 35434271, 2022). "In glioma cells, knockdown of ENO1 resulted in the restoration of E-cadherin expression and suppression of vimentin expression." (PMID 35434271, 2022). "As inhibitor of ENO1, the derivatives of 2 preferentially inhibits glycolysis in ENO1-null over isogenic ENO1-rescued glioma cells." (PMID 34671213, 2021). "Metabolomic profiling of CB-839 treated ENO1-deleted, isogenic rescued, and intact glioma cells underscored the importance of exogenous pyruvate, as CB-839 treatment resulted in significant TCA cycle metabolite depletion only in the absence of pyruvate." (PMID 34172075, 2021). "We found that glioma cells with ENO1 homozygous deletions are selectively sensitive to CB-839; however, this was entirely reversed by exogenous pyruvate supplementation." (PMID 34172075, 2021). "First, we performed a systematic metabolomic analysis to determine the effects of the enolase inhibitor prodrug, POMHEX, on cultured glioma cells varying in ENO1-deletion status." (PMID 34172075, 2021). "Another group confirmed that lncRNA SNHG18 promoted glioma cell motility by disrupting the nucleocytoplasmic shuttling of ENO1." (PMID 34627260, 2021). "Using this concept of collateral lethality, we validated that in a subset of gliomas with 1p36 deletions, passenger deletion of the glycolytic gene ENO1 selectively renders cancer cells sensitive to inhibition of the redundant isoform ENO2." (PMID 34172075, 2021). "Given the interplay of pyruvate and glutamine to sustain the TCA cycle, we reasoned that these two arms of anaplerosis are redundant and together present a targetable metabolic liability in ENO1-deleted glioma cells." (PMID 34172075, 2021). "SNHG18 inhibits the nuclear and cytoplasmic transport of ENO1 to promote the occurrence and metastasis of glioma." (PMID 34215720, 2021).
glioma (continued). "We analyzed polar metabolites in sensitive (ENO1-deleted) and resistant (ENO1-WT) glioma cells treated with enolase and glutaminase inhibitors." (PMID 34172075, 2021). "Previous study has confirmed that ENO1 attenuated led to underpin cancer progression in glioma cells." (PMID 34772911, 2021). "We also found that under nutrient conditions that approximate the in vivo metabolic environment, glutaminase inhibition has only modest effects even in ENO1-deleted glioma cells, which are quite sensitive in “normal” media." (PMID 34172075, 2021). "Since an intracranial orthotopic tumor would be the most faithful model for human glioma, we established ENO1-deleted intracranial tumors in immunocompromised Foxn1nu/nu nude mice." (PMID 34172075, 2021). "This suggests that ENO1-deleted glioma cells minimally depend on glutamine as a fuel to support anaplerosis in vivo." (PMID 34172075, 2021). "Phosphorylated AMPK (T172) is observed in ENO1-deleted D423 glioma cell line, which induce growth inhibition and subsequent apoptosis 23,85." (PMID 34671213, 2021). "Recent studies have shown that ENO1 has a pivotal role in different tumor tissues, such as head and neck cancers, Non-Hodgkin’s lymphoma, breast cancer, cholangiocarcinoma, glioma, and GC27–29." (PMID 33067426, 2020). "Decades of research have shown that in addition to its normal glycolysis function, ENO1 is involved in several key biological processes in glioma and other cancers, including proliferation, migration, and invasion." (PMID 31798634, 2019). "Though ENO1 did not affect the radiosensitivity significantly, knockdown of ENO1 expression using a small interfering RNA significantly suppressed the invasion-promoting action induced by SNHG18-overexpression in glioma cells." (PMID 31798634, 2019). "Increased levels of ENO1 protein were proven to be an important predictor of poor prognosis in patients with glioma." (PMID 31798634, 2019). "The ability of SNHG18 to regulate glioma cell motility depends on disrupting ENO1 nucleocytoplasmic transport." (PMID 31798634, 2019). "The expression of ENO1 is higher in glioma samples than in normal brain tissues, and is located mainly in the cytoplasm of glioma tissues, with weak expression in the cytoplasm in normal brain tissues." (PMID 31798634, 2019). "In summary, SNHG18 regulates the progression of EMT and the organization of the cytoskeleton into lamellipodia by repressing the nucleocytoplasmic transport of ENO1 in glioma cells." (PMID 31798634, 2019). "To explore the correlation between WBP2 and ENO1 activity, we determined the ENO1 values in six groups of glioma cells (EGFP-Vector, EGFP-WBP2, WBP2 + siNC, WBP2 + siENO1, WBP2 + siWBP2, and WBP2 + siHomer3)." (PMID 29497031, 2018). "ENO1 is a hub protein in the Embden–Meyerhof–Parnas (EMP) pathway providing energy for glioma tumor cells." (PMID 29497031, 2018). "As a negative regulator of the PI3K/Akt pathway, depleted expression of ENO1 suppresses proliferation, metastasis, and invasive progression of glioma cells." (PMID 29497031, 2018). "This is the first report of the molecular mechanisms of ENO1 in NSCLC, even more in-depth than our previous report of ENO1 in glioma." (PMID 25887760, 2015). "We found that ENO1 was mainly localized in the cytoplasm of glioma tissues while weakly expressed in cytoplasm in NB tissues." (PMID 24650096, 2014). "To further study the mechanism by which ENO1 regulates cell proliferation, migration and invasion, we examined protein levels of cell cycle and EMT-associated genes in glioma U251 and U87 cells with stably suppressed ENO1 expression." (PMID 24650096, 2014). "In this investigation, we examined key cell growth regulators and observed that Cyclin D1, Cyclin E1, pRb, and NF-κB were downregulated after stable ENO1 knockdown in glioma U251 and U87 cells." (PMID 24650096, 2014). "Compared with NB tissues, glioma tissues exhibited higher expression levels of ENO1 mRNA (P < 0.0001)." (PMID 24650096, 2014).
glioma (continued). "In order to assess the role of ENO1 in glioma, we performed real-time PCR to measure the expression of ENO1 mRNA transcripts in 45 freshly collected glioma tissues and 15 freshly collected NB tissues." (PMID 24650096, 2014). "Multivariate analyses showed that increased expression of ENO1 protein was a significant predictor of poor prognosis for glioma patients." (PMID 24650096, 2014). "We also observed that the expression level of ENO1 was positively correlated with tumor grading as there was a significant difference between high and low grade gliomas." (PMID 24650096, 2014). "Mechanistic analyses revealed that Cyclin D1, Cyclin E1, pRb, and NF-κB were downregulated after stable ENO1 knockdown in glioma U251 and U87 cells." (PMID 24650096, 2014). "ENO1 protein (48 kDa) was found to be up-regulated in 10 cases of glioma (WHO IV) compared with 4 NB tissues by Western blot (P < 0.0001)." (PMID 24650096, 2014). "The results indicated that the level of ENO1 expression was an independent prognostic factor for glioma (P < 0.001)." (PMID 24650096, 2014). "In the 136 glioma cases with survival data, we observed that the level of ENO1 protein expression was significantly correlated with overall survival." (PMID 24650096, 2014). "We also measured the expression levels and subcellular localization of ENO1 protein in 136 archived paraffin-embedded glioma samples and 15 NB tissues using immunohistochemical staining." (PMID 24650096, 2014). "We used immunohistochemistry to further examine the expression level and subcellular localization of ENO1 in glioma and NB tissues." (PMID 24650096, 2014). "Our data indicated that knockdown of ENO1 resulted in restoration of E-cadherin expression and suppression of Vimentin expression in glioma cells." (PMID 24650096, 2014). "We found that stably decreased expression of ENO1 by shRNA inhibited glioma cell proliferation, migration, and invasion in vitro and decreased tumorigenesis in vivo compared to the PLVM-Ctr groups." (PMID 24650096, 2014). "ENO1 protein was highly expressed in 69.1% (94/136) of glioma samples, while only in 20.0% (3/15) of NB samples, a significantly lower frequency (P < 0.001)." (PMID 24650096, 2014). "Consistent with mRNA levels, ENO1 protein expression was significantly elevated in 10 glioma samples compared to 4 NB tissues." (PMID 24650096, 2014). "This inhibitor is a racemic mixture and a cell-permeable pivaloyloxymethyl (POM) prodrug of HEX, which can selectively kill ENO1-deleted glioma cells at low-nanomolar concentrations and eradicate intracranial orthotopic ENO1-deleted tumors in mice at doses well-tolerated in non-human primates." (PMID 36588153, 2023). "Another group reported overexpression of mRNA and protein levels of ENO1 in glioma samples." (PMID 38139462, 2023). "Also, the glycolytic activity of ENO1 has been correlated with the expression of ATP citrate lyase genic expression (ACL) in glioma cells, considering ENO1 as a metabolic tumor promoter." (PMID 38139462, 2023). "Therefore the authors suggest that the function of ENO1 in the glioma cells depends on ENO1 subcellular localization." (PMID 38139462, 2023). "The overexpression of ENO1 is linked to glioma progression, and its knockdown resulted in the suppression of cell growth, migration, and invasion progression by inactivating the PI3K/Akt pathway in glioma cells." (PMID 36672262, 2023). "DePinho and colleagues found that ENO1 was often deleted in glioblastomas and rendered glioma cells more sensitive to the inhibition of ENO2, herein proposed collateral damage caused by passenger deletions of redundant essential genes as a novel therapeutic strategy." (PMID 35156101, 2021). "ENO1 knockdown has been shown to result in suppressed glioma cell growth." (PMID 33937086, 2021). "ENO1-intact glioma cells can recover more quickly from enolase inhibition." (PMID 34671213, 2021).
glioma (continued). "Metabolomic profiling of ENO1-deleted glioma cells treated with the enolase inhibitor revealed a profound decrease in the TCA cycle metabolites with the toxicity reversible upon exogenous supplementation of supraphysiological levels of anaplerotic substrates, including pyruvate." (PMID 34172075, 2021). "Yet, despite a promising observation with CB-839 in vitro, we found that in vivo, glutamine may not be a prominent anaplerotic substrate and that glucose-derived pyruvate predominantly drives anaplerosis, at least in ENO1-deleted gliomas." (PMID 34172075, 2021). "We observed that regardless of ENO1 status, glutamine was essential for glioma cell growth as cells grown in glutamine-deficient medium displayed substantially delayed growth, confirming previous findings that cancer cells are “addicted” to glutamine in vitro." (PMID 34172075, 2021). "In this study, we brought together our novel inhibitors of enolase, HEX, and POMHEX, as well as the glutaminase inhibitor CB-839, to investigate the redundancies between glycolysis and glutaminolysis for supporting tumor growth and viability in vitro and in vivo in ENO1-deleted gliomas." (PMID 34172075, 2021). "Additionally, ENO1 has also been seen as a potential prognostic biomarker in breast, head and neck cancers, and gliomas." (PMID 32197468, 2020). "Thus, the interaction between SNHG18 and ENO1 probably regulates the nucleocytoplasmic transport of ENO1 in glioma cells." (PMID 31798634, 2019). "In turn, another study showed that β-catenin served as a downstream effecter of ENO1 in glioma." (PMID 31431517, 2019). "Furthermore, in vitro and in vivo experiments indicated that the oncogenic role of WBP2 in glioma was through modulating ENO1 and glycolysis activity via the ENO1-PI3K/Akt signaling pathway." (PMID 29497031, 2018). "Our data indicated that ENO1 and Homer3 had high coverage rates with WBP2, and previous studies have confirmed that both ENO1 and Homer3 are associated with glioma and nervous system development, suggesting these two proteins are an integral part in WBP2-mediated glioma cell growth and metastasis." (PMID 29497031, 2018). "However, we did not observe any EC cell morphology changes, a result consistent with our previous report of ENO1 function in glioma." (PMID 25951350, 2015). "Downregulation of ENO1 by siRNA inhibited cell migration and invasion in glioma cells." (PMID 26017754, 2015). "To determine whether ENO1 is an independent prognostic factor for glioma, we performed multivariate analysis of ENO1 expression adjusted for the same parameters." (PMID 24650096, 2014). "Interestingly, similar results were also observed in siRNA-mediated suppression of ENO1 in glioma cells." (PMID 24650096, 2014). "In summary, ENO1 expression may have significant value as an unfavorable progression indicator for glioma patients." (PMID 24650096, 2014). "Together these findings suggest that ENO1 may play a unique role in the Warburg effect of glioma cells." (PMID 24650096, 2014). "Subsequently, we examined the effect of decreased ENO1 expression on glioma cell growth in vitro." (PMID 24650096, 2014). "First, we confirmed that ENO1 mRNA levels were higher in 45 glioma samples than in 15 NB tissues." (PMID 24650096, 2014). "However, we observed that the expression level of ENO1 was positively correlated with the status of pathology classification (WHO I-II vs. WHO III-IV) (P = 0.000) in glioma patients." (PMID 24650096, 2014). "ENO1 expression levels were examined in glioma tissues and normal brain (NB) tissues." (PMID 24650096, 2014). "ENO1 mRNA and protein levels were upregulated in glioma tissues compared to NB." (PMID 24650096, 2014). "Thus, SNHG18 overexpression's effects on glioma cells depended at least in part on ENO1." (PMID 31798634, 2019).